CHRM5 (cholinergic receptor muscarinic 5)
Description:
The muscarinic acetylcholine receptor mediates various cellular responses, including inhibition of adenylate cyclase, breakdown of phosphoinositides and modulation of potassium channels through the action of G proteins. Primary transducing effect is Pi turnover.
Synonyms: HM5
Tractability: Small molecule: an approved drug acts on it; a structure with a bound ligand is known; a high-quality ligand is known; it belongs to a druggable protein family. Antibody: its Gene Ontology location is reachable by antibodies, with high confidence; UniProt places it where antibodies can reach, with medium confidence; UniProt predicts a signal peptide or a membrane-spanning region. PROTAC: a small molecule that binds it is known.
Target class: Small molecule receptor (family A GPCR); Acetylcholine receptor; Monoamine receptor; Family A G protein-coupled receptor; Membrane receptor
Chemical probes: ML172, ML326, ML375, ML380, ML381, VU 0238429
Safety:
Unwanted effects reported when the protein is acted on. In parentheses: how it was acted on, where the effect was seen, and who reports it.
increased salivation (activation, acute dosing; nervous system; source: Lynch et al. (2017))
Gene: Protein-coding gene on chromosome 15 (33,968,497 to 34,067,458, forward strand). Ensembl gene ENSG00000184984.
Subcellular location: Cell membrane; Postsynaptic cell membrane
Pathways (Reactome):
Signal Transduction: G alpha (q) signalling events; Muscarinic acetylcholine receptors
Gene Ontology:
Molecular function: protein binding; G protein-coupled acetylcholine receptor activity; phosphatidylinositol-4,5-bisphosphate phospholipase C activity; G protein-coupled receptor activity
Biological process: adenylate cyclase-inhibiting G protein-coupled acetylcholine receptor signaling pathway; chemical synaptic transmission; G protein-coupled acetylcholine receptor signaling pathway; G protein-coupled receptor signaling pathway, coupled to cyclic nucleotide second messenger; acetylcholine receptor signaling pathway; G protein-coupled receptor signaling pathway; gastric acid secretion; regulation of phosphatidylinositol dephosphorylation
Cellular component: dendrite; plasma membrane; synapse; membrane; postsynaptic membrane
Genetic constraint (gnomAD): Loss-of-function variants: 18 observed, 41.12 expected, observed/expected ratio (o/e) 0.44, 90% interval 0.3 to 0.65. The upper end of that interval is the gene's LOEUF score, 0.65, which puts it in group 2 of 6, group 1 being the genes least tolerant of losing a copy. Missense variants: 515 observed, 687.29 expected, observed/expected ratio (o/e) 0.75, 90% interval 0.7 to 0.81. Synonymous variants: 241 observed, 260.5 expected, observed/expected ratio (o/e) 0.93, 90% interval 0.83 to 1.03.
Homologues: Orthologues: chimpanzee CHRM5 (99% identical), macaque CHRM5 (96% identical), rabbit CHRM5 (89% identical), mouse Chrm5 (89% identical), rat Chrm5 (89% identical), guinea pig CHRM5 (86% identical), dog CHRM5 (85% identical), pig CHRM5 (82% identical), tropical clawed frog chrm5 (70% identical), zebrafish chrm5a (59% identical), zebrafish chrm5b (54% identical). Paralogues in human: CHRM3 (51% identical), CHRM1 (46% identical), CHRM4 (38% identical), CHRM2 (37% identical), HRH1 (23% identical), HTR1A (20% identical), HRH3 (20% identical), DRD1 (19% identical), DRD5 (19% identical), HTR4 (19% identical), HTR1D (19% identical), HRH2 (18% identical), and 13 more.
Diseases named in the same sentence as CHRM5 in open-access papers:
CHRM5 is named in the same sentence as 22 diseases in open-access papers, as found by Europe PMC text mining. Sharing a sentence is not in itself a finding about the gene and the disease. The quoted sentences say what the papers report.
COVID-19 (2 papers, 2022). A disease caused by infection with severe acute respiratory syndrome coronavirus 2. "In this context, autoantibodies such as ACE2-aab, AGTR2-aab, BDKRB1-aab, CXCR3-aab, MAS1-aab, CHRM5-aab, NRP1-aab, F2R-aab, STAB1-aab appeared to play a major role in stratifying COVID-19 by disease burden." (PMID 35264564, 2022). "Follow-up analysis indicated that CXCR3-aab, AGTR1-aab, MAS1-aab, CHRM5-aab, and BDKRB1-aab were the five most significant predictors of COVID-19 disease-severity classification based on the number of nodes and the Gini decrease criteria for measuring variable importance." (PMID 35264564, 2022). "Interestingly AABs to the vaso- and immunoregulatory receptors CXCR3, CHRM5, BDKRB1, MAS1, AGTR1, F2R/PAR-1, and STAB1 were the most significant classifiers of acute COVID-19 severity in our recent study." (PMID 36238301, 2022).
alcohol addiction (1 paper, 2007). "Our data suggest that variation within the CHRM5 locus may play an important role in tobacco and cannabis but not alcohol addiction in European ancestry populations." (PMID 17608938, 2007).
alcohol dependence (1 paper, 2007). Physical and psychological dependence on alcohol. "This mode of action, specifically the predominant role of ethanol in neurones afferent to the mesolimbic dopamine/M5R-containing neurones may in part explain the lack of association seen between CHRM5 and alcohol dependence and dose in this study." (PMID 17608938, 2007).
Alzheimer disease (1 paper, 2024). A progressive, neurodegenerative disease characterized by loss of function and death of nerve cells in several areas of the brain leading to loss of cognitive function such as memory and language. "Additionally, the impaired cholinergic dilation of cerebral blood vessels in CHRM5‐knockout mice implies that M5 mAChR may play a role in the pathophysiology of Alzheimer's disease and focal cerebral ischemia." (PMID 37842807, 2024).
cannabis dependence (1 paper, 2007). Physical and psychological dependence on the drug cannabis. "Our overall hypotheis was that CHRM5 would influence tobacco, alcohol and cannabis dependence." (PMID 17608938, 2007).
cognitive deficits (1 paper, 2024). "CHRM5‐knockout mice display decreased prepulse inhibition (a model of psychosis) and cognitive deficits associated with CNS neuronal and cerebrovascular abnormalities." (PMID 37842807, 2024).
diabetes (1 paper, 2025). "CHRM5 rs7162140, which yielded the strongest associations in our study, has previously been linked to drug addiction, and some authors have suggested that its association of this SNP with diabetes may be driven by its role in shaping risk behaviors that predispose to the disease." (PMID 41153348, 2025).
drug dependence (1 paper, 2007). "Our data does not support the role of CHRM5 as a generalised risk factor for drug dependence." (PMID 17608938, 2007).
glioma (1 paper, 2018). A benign or malignant brain and spinal cord tumor that arises from glial cells (astrocytes, oligodendrocytes, ependymal cells). "A peptide corresponding to ACM5 (CHRM5) was differentially phosphorylated in restricted glucose, but there are limited reports on the potential role of this muscarinic receptor in glioma." (PMID 29946469, 2018).
ischemia (1 paper, 2025). A hypoperfusion of the BLOOD through an organ or tissue caused by a PATHOLOGIC CONSTRICTION or obstruction of its BLOOD VESSELS, or an absence of BLOOD CIRCULATION. "Namely, the peptide reduced the expression of many genes (e.g., P2rx6, Gabra3, Grik4, Oprl1, Glra2, Crhr1, Hrh1, Chrm5, Grik1) related to the neurosignaling system and whose expression was not significantly changed by ischemia itself." (PMID 40650034, 2025).
myopia (1 paper, 2013). "Comparison between muscarinic receptor mutants showed that M1 (Chrm1), M4 (Chrm4) and M5 (Chrm5) mutants had significantly higher myopia in the lens-treated eyes than did M2 and M3 mutants." (PMID 23649821, 2013).
pancreatic cancer (1 paper, 2012). "The contributing genes to this pathway, e.g. CCKBR, CHRM5, EDNRA, LPAR1, SSTR2/3, and SCTR, have diverse functions in regulating the endocrine and exocrine functions of the pancreas, which are highly relevant to pancreatic cancer." (PMID 23056513, 2012).
schizophrenia (1 paper, 2007). A major psychotic disorder characterized by abnormalities in the perception or expression of reality. "Consequently, the linkage of the CHRM5-CHRNA7 haplotype with schizophrenia is unlikely to represent evidence due to linkage disequilibrium with functional markers in either gene." (PMID 17608938, 2007).
substance dependence (1 paper, 2007). The psychological or physiological need to take a substance in order to experience its effects or to avoid the effects of its absence. "We show that CHRM5 the gene that codes for the M5R contains variations that influence the risk of substance dependence and dose in a population of young adults." (PMID 17608938, 2007). "In addition to the role in substance dependence, CHRM5 may also be important in other psychiatric disorders where dysregulation of dopaminergic neurotransmission has been implicated." (PMID 17608938, 2007).
cancer (2 papers, 2021 to 2025). A tumor composed of atypical neoplastic, often pleomorphic cells that invade other tissues. "The MHCF1 unique mutations consisted of protein misfolding (Hsp-related genes) and acetylcholine receptor (Chrnb4 and Chrm5) genes that possibly act on cancer cell processes, and tumor suppressor (Adamts1 and Adamts5) and cell cycle (Aurkb and Bub1) genes." (PMID 34158541, 2021).
infection (1 paper, 2022). The state of being infected such as from the introduction of a foreign agent such as serum, vaccine, antigenic substance or organism. "After adjustment for the potential confounders, sex, age, and time since infection, we found in addition to CHRM5-Ab significant differences with higher levels of AABs against CHRM1 and F2R/PAR-1 while lower levels of ADRB1, CHRNA1, and EDNRA in PCS/ME/CFS than in PCS/non-ME/CFS groups." (PMID 36238301, 2022). "Except for CHRM5-Ab, differences in AAB levels between patient groups were found only after adjustment for age, gender, and disease duration (time after infection), indicating that PCS patients with and without ME/CFS only barely differ in their AAB levels." (PMID 36238301, 2022).
CHRM5 also shares sentences with these, for which no sentence is quoted: tumor (2 papers); African trypanosomiasis (1); dementia (1); malaria (1); psychiatric disorder (1); psychosis (1).